SETD2 (SET domain containing 2, histone lysine methyltransferase)
Diseases named in the same sentence as SETD2 in open-access papers (continued):
Sharing a sentence is not in itself a finding about the gene and the disease.
cancer (continued). "Consistent with our predictions and observations in other cancers, CpGs that are hypomethylated in SETD2 cases show strong enrichment in the gene bodies whereas hypermethylated CpGs do not." (PMID 37528416, 2023). "Among the 19 CIMP-positive cancers, very few shared potential driver events, and those drivers were only IDH1 and SETD2 mutations." (PMID 35134107, 2022). "These fundamental insights are important to understand SETD2’s role in disease, most notably in cancer in which SETD2 is frequently inactivated." (PMID 35661267, 2022). "Other genes implicated in aberrant DNA methylation in cancer include the TET family of genes and SETD2." (PMID 35761387, 2022). "SETD2 (SET domain-containing 2), a methyltransferase protein that is often mutated in many cancers, is responsible for the methylation of H3K36 histone." (PMID 35406498, 2022). "This important finding provides an opportunity to selectively target SETD2 deficient cells, making it a potential much-needed avenue to develop a targeted therapy for cancers in which SETD2 activity is perturbed." (PMID 35661267, 2022). "SETD2’s function can also be affected in cancer through misregulated expression of the demethylase KDM4A, which demethylates both H3K36me3 and H3K9me3." (PMID 35661267, 2022). "Despite being frequently inactivated in cancer, SETD2 is an essential gene in several human cell lines." (PMID 36052643, 2022). "The availability of specific small-molecule inhibitors of SETD2 would serve as important chemical probes to investigate the role of SETD2 in cancer and other diseases." (PMID 34576219, 2021). "This is in line with our observation of an increased personal history of cancer, including cancer beyond CMM and RCC, in cases with CLTCL1 or SETD2 mutations." (PMID 34067022, 2021). "Epigenetic reprogramming is a central feature of ccRCC, and the reduction of SETD2 can lead to a large-scale transcriptional dysregulation in cancer cells, so SETD2 is defined as a driving gene in ccRCC." (PMID 34715919, 2021). "For example, elevated levels of α-tubulin acetylation correlate positively with metastatic potential and αTAT inhibits cancer cell motility, whereas SETD2-mediated tubulin methylation corresponds with genomic stability and correct mitotic spindle formation." (PMID 34157286, 2021). "Multiple cancers have concomitant VHL, PBRM1, and SETD2 mutations, and all these genes map to chromosome 3p." (PMID 34715919, 2021). "Concerning additional cancer genes identified in the significantly altered regions, some were characterized as known drivers (SETD2, BAP1, FLT4 and PTEN) and others as predicted drivers (FGFR4 and NSD1), according to the CGI." (PMID 33668731, 2021). "MSIsensor scores in patients with SETD2 mutant cancer (0.12; 0.01–0.84) were significantly higher than the scores in patient with SETD2 nonmutant cancer (0.05, 0.00–0.31; P < 0.0001)." (PMID 34127768, 2021). "In TCGA cohort, higher TMB was observed in patients with SETD2 mutant cancer (median, 5.9; interquartile range, 1.8–29.2) than those in patients with SETD2 nonmutant disease (1.5, 0.7–3.3; P < 0.0001)." (PMID 34127768, 2021). "Variance in the data, as well as the maximum instability values observed (absolute values), were higher in the JMJD1B mutant population than in the SETD2 mutants, in all four cancers analyzed." (PMID 32070414, 2020). "In numerous experimental settings, it has been established that SETD2 regulate cell growth in human cancers." (PMID 30755832, 2019).
cancer (continued). "This raises an urge to identify novel, more potent agents or to find an alternative approach to target SETD2-dependent functions in cancer." (PMID 30818762, 2019). "A second set consisted of an additional 15 cancer-related genes (Nf1, Mki67, Mllt4, Fgfr2, Ctnnb1, Fat1, Clp1, Fat4, Arid1a, Nat1, Nat2, Setd2, Impg1, Nbas and Npat)." (PMID 29925311, 2018). "Loss of function mutations of the tumor suppressor SET domain containing 2 (SETD2), overexpression of oncogene lysine demethylase 4A (KDM4A), or mutation of histone H3.3 can decrease H3K36me3 in cancer." (PMID 30356299, 2018). "Recent studies have provided novel insight about the involvement of SETD2 protein in pathways connected to cancer." (PMID 28812986, 2017). "Like in other cancers, reduced H3K36 trimethylation in DCGs with SETD2 mutation was confirmed by immunohistochemistry, indicating that epigenetic regulation was altered in these tumors." (PMID 28852847, 2017). "The Genomics of Drug Sensitivity in Cancer database lists four chemical compounds with a selective inhibitory capacity for SETD2−/− cell lines." (PMID 27191891, 2016). "Our study defines the genetic inactivation of SETD2 as a hallmark of EATL-II, and shows for the first time highly prevalent SETD2 deregulation in a cancer of mature lymphocytes." (PMID 27600764, 2016). "In fact, mutations in ccRCC are frequently observed in epigenetic factors such as the chromatin-remodeler PBRM1 and the histone modifying enzymes BAP1 and SETD2, highlighting the central role of epigenetic regulation in this particular cancer." (PMID 26575290, 2015). "The wt ccRCC cell line Caki2 showed the highest SETD2 expression levels, comparable with those of a non-cancer kidney epithelial cell line (HEK293)." (PMID 26575290, 2015). "Third, mutations in chromatin regulatory factors such as SETD2, ARID1, SMARCA4, KDM6A, EP300 and MLL are emerging in various cancer types but, so far, only a few have been linked to altered methylome patterns." (PMID 25473433, 2014). "It is also unclear how SETD2 impacts the aggressiveness of the cancer." (PMID 41602827, 2026). "While the specific role of SETD2-catalyzed H3K36me3 in cancer pathogenesis remains unclear, it is intriguing that the di-methyl and tri-methyl states at H3K36 may have profoundly different impacts on tumorigenesis." (PMID 40462961, 2025). "However, as resistance to all kinds of therapies is one of the main critical barriers to effective cancer treatment, several studies have been conducted to determine the role of SETD2 in cell resistance." (PMID 39591760, 2025). "Furthermore, re-analysis of data from a published CRISPR knockout screen revealed that SETD2 is a selective vulnerability of ALT-positive cancers." (PMID 39921567, 2025). "It is evident from the data that genes such as VHL, TTN, BAP1, PBRM1, and SETD2 are consistently identified as the most frequently mutated genes in KIRC, underscoring their potential importance as key drivers of tumorigenesis in this specific cancer subtype." (PMID 40649942, 2025). "SETD2 inactivation in cancer cells can sensitizes cancer cells to immune checkpoint inhibitors." (PMID 40959108, 2025). "Given SETD2's key role in HR and DSB repair, its deficiency may sensitize cancer cells to PARP inhibition, positioning SETD2 as a compelling therapeutic target for such strategies 82-83." (PMID 40959108, 2025). "This is in line with the available literature on other cancer types, which also demonstrates that the majority are missense or frameshift mutations and a distinct lack of mutation hotspots in SETD2." (PMID 41228333, 2025). "In both these cancer types, high SETD2 expression correlates with worse patient outcomes." (PMID 40961184, 2025).
cancer (continued). "Our observation that SETD2 loss drives an inflammatory gene expression signature accompanied by cytokine secretion is also consistent with a recent study of MLL3, a histone methyltransferase mutated in many cancers." (PMID 37418588, 2024). "However, interestingly, in the same cancer clone as NF2, we identified a potential BRCA2 driver mutation (p.E51K) present in all tumors along with a SETD2 (p.S1885N) mutation present only in the recurrence." (PMID 39935847, 2024). "To test whether methylation changes had any impact on cancer genes, we examined which of the differentially methylated CpGs in SETD2 cases were correlated with the expression of known cancer genes." (PMID 37528416, 2023). "To understand how Setd2 deficiency increases chromatin accessibility to induce the expression of KRAS signature, we first focused on Etv1, one of the transcription factors downstream of ERK signaling and a well-defined oncogene in multiple cancer types." (PMID 36810256, 2023). "Therefore, SETD2 is considered a potential epigenetic therapeutic target and is the subject of ongoing research on cancer-related diagnosis and treatment." (PMID 37025591, 2023). "It has been reported that SETD2 plays an important role in cancer." (PMID 37962020, 2023). "In fact, ccRCC is the most common SETD2-inactivated cancers." (PMID 36230766, 2022). "We expected further clinical studies to investigate the prognostic implications of SETD2 in cancer." (PMID 36035179, 2022). "SETD2, BAP1, and MTOR possessed higher mutation frequencies in the high-risk group than in the low-risk group implying that these three cancer-driven mutations may promote the progression of KIRC." (PMID 37342680, 2022). "Furthermore, the SETD2-mediated manipulation of ATG12 isoforms expression ratio in these cancer cells has an impact on their migration capability." (PMID 35585060, 2022). "Indeed, candidate genes involved in maintaining genome stability, such as RAE1, SETD2, and CLTCL1, are attractive candidates for broad cancer susceptibility." (PMID 34067022, 2021). "This association remained robust after adjusting for confounding factors, including age, sex, cancer type, treatment strategy, and TMB, suggesting SETD2 mutation was not a prognostic, but a predictive biomarker for cancer immunotherapy." (PMID 34127768, 2021). "In past decades, the study of SETD2 primarily focuses on their function in cancer biology." (PMID 34663428, 2021). "Besides naturally occurring splice variants, many missense and truncation mutations that can potentially alter the half-life are found in SETD2 of patients with cancer." (PMID 34391778, 2021). "SETD2 is a tumor suppressor gene expressed in different cancer types." (PMID 33407425, 2021). "In line, detailed survival analysis in our cohort indicated significantly worse cancer-specific survival probability for patients with metastases harbouring multiple somatic drivers and VHL wildtype alleles compared to PBRM1, SETD2, and VHL monodrivers (p (logrank) = 0.03)." (PMID 34944839, 2021). "A better understanding of histone and tubulin methylation by SETD2 could also drive anticancer drug development and thus could provide new therapeutic targets to help cancer patients." (PMID 34157286, 2021). "More PD-L1-positive tumors and higher TMBs were discovered in patients with SETD2 mutant cancer." (PMID 34127768, 2021). "In some cancer cell lines, the depletion of SETD2/H3K36me3 can lead to mutant phenotypes." (PMID 34715919, 2021). "However, we clearly demonstrate the presence of subclonal NF2 mutations in three patients, characterized by clonal mutation in other key MPM mutated cancer genes including BAP1, SETD2, and the TERT promoter." (PMID 34261524, 2021).
cancer (continued). "Some evidence for this is provided by studies on human cancers which show that the total H3K36me3 levels are not significantly impacted by a monoallelic loss of SETD2." (PMID 33023640, 2020). "Unlike other KMTs that catalyze methylation to cause cancer development and cancer drug resistance, methylation induced by SETD2 can actually inhibit cancer growth and reverse drug resistance." (PMID 32859239, 2020). "Targeting SETD2 is believed to be a promising strategy for cancer therapy." (PMID 30755832, 2019). "We also observed somatic variants in several known cancer-associated genes (for example, JAG1, PRDM2, PRDM8, SETD2, ASPM, ZIC, GRIK1, etc.), which may be important for cell growth and proliferation." (PMID 30871634, 2019). "The role of SETD2 and the H3K36me3 histone mark in cancer is controversial." (PMID 30818762, 2019). "Besides the well-known MPM-associated genes, CDKN2A, NF2 and BAP1, other interesting cancer-associated genes were listed as frequently involved in a copy number loss (e.g. EP300, SETD2 and PBRM1)." (PMID 29371938, 2017). "The study of ccRCC demonstrated that SETD2 mutation causes loss of H3K36 trimethylation and consequently leads to altered chromatin accessibility and widespread defects in transcript processing that eventually result in promotion of cancer development." (PMID 28852847, 2017). "SETD2, PTEN, RNF43, HRAS, EPHA2, and BAP1 were also linked to primarily positive associations in more than one cancer type, suggesting that they may play a general role in CGI hypermethylation." (PMID 29125844, 2017). "In addition, future studies should be integrated with genomics data to assess the effects of mutations of genes commonly mutated in ccRCC (e.g. VHL, SETD2, BAP1) on the cancer kinome." (PMID 28418903, 2017). "In the literature, no clues can be found of heterozygous SETD2 knockout mice being predisposed to any kind of disease or cancer." (PMID 27191891, 2016). "The importance of epigenetic regulation in cancer is also underscored by the findings that a number of genes encoding critical epigenetic regulators, including MLL1, MEN1, EZH2, SETD2, JARID1C, BAF180 and UTX, have been identified as mutated in various human cancers." (PMID 21544224, 2011). "Therefore, to explore whether SETD2 may enhance cancer cell killing by immune cells, we focused on NK cells as enhanced cancer cell killing has been reported with ferroptosis agents." (PMID 40961184, 2025). "Furthermore, SETD2 gene translocations have been described in several types of cancers." (PMID 39591760, 2025). "Therefore, SETD2 depletion both enhances resistance to ferroptosis induction and may contribute to how some cancers evade immunosurveillance." (PMID 40961184, 2025). "In addition, further investigation of predictive biomarkers is needed for the selection of patients with SETD2 alterations who may derive a response to WEE1 inhibitors alone or in combination with other cancer-directed therapies." (PMID 38920407, 2024). "When analyzing pooled data from patients with different cancer types, our results showed higher levels of infiltrating of CD8 cells, lower levels of infiltrating of M2 macrophages, higher TMB, and higher expression of immune checkpoint molecules in the SETD2 deleterious mutation group." (PMID 37479966, 2023). "We hypothesize that SETD2-deficient cancer may be more sensitive to the inactivation of ASF1A and ASF1B than SETD2-proficient cancer if SETD2 loss–induced increase in histone exchange is required for creating a permissive epigenetic landscape to enhance oncogenic transcriptional output." (PMID 36810256, 2023).
cancer (continued). "SETD2 encodes a methyltransferase that specifically trimethylates lysine-36 of histone H3 (H3K36me3), whereas KDM5c (also known as JARID1C) is a gene that encodes an H3K4me2/3 demethylase that plays a central role in transcriptional repression and can mediate cancer progression." (PMID 34439859, 2021). "Fortunately, there are less significantly mutated genes in ccRCCs compared with other cancers; the top four most commonly mutated genes are von Hippel-Lindau (VHL) tumor suppressor gene, polybromo-1 (PBRM1), BRCA1-associated protein 1 (BAP1), and SET domain containing 2 (SETD2)." (PMID 32185138, 2020). "However, the complete loss of SETD2 function was not necessary to initiate the cancer phenotype or metastasis, and a gradual decline in H3K36me3 is due to adaptation processes or mediated by other mechanisms while developing distant metastasis." (PMID 28812986, 2017). "Besides VHL and SETD2, the compound was also selective for cancer cells with mutation in PTEN and CDKN2A (data not shown)." (PMID 25853938, 2015). "Additionally, late-stage SETD2-mutated cancers may not be fully represented in this study, and thus a survival bias may be introduced." (PMID 41228333, 2025). "This raises the possibility of a complementary role for SETD2 and ZMYND11 in antagonizing cancer development, forming a coordinated axis in which SETD2-catalyzed H3K36me3 promotes ZMYND11 recruitment and inhibits KMT2A." (PMID 41279818, 2025). "Combination regimens involving SETD2 inhibitors with WEE1 inhibitors, HDMIs, or PARPis have demonstrated encouraging therapeutic efficacy in preclinical cancer models and are expected to form the basis for new treatment strategies for prostate cancer." (PMID 40959108, 2025). "In cancer stem cells of the liver, HOTAIR blocked the recruitment of CREB, P300, and RNA polymerase II (Pol II) to the SETD2 promoter region." (PMID 39280246, 2024). "To delve further into the impact of ALKBH1 mutations on STAD, we explored their interactions with other common genes involved in cancer progression, including TTN, PBRM1, and SETD2." (PMID 38317214, 2024). "Other molecules, such as FOXA1, SETD2, Hes5, C/EBP-δ, PRMT5, METTL3, Piwil1, PLK1, ERK1/2, and a series of miRNA, indirectly modulate the sensitivity of cancer cells to drugs by regulating FBXW7." (PMID 36998461, 2023). "We also found that other known cancer-related genes were also altered at low frequency including APC (n = 5), KRAS (n = 2), SETD2 (n = 2), DAXX (n = 1) and STAG2 (n = 1)." (PMID 37524847, 2023). "The TMB of a total of 6721 patients form different cancer types was calculated and the TMB was compared between SETD2 mut + and SETD2 mut- groups." (PMID 37479966, 2023). "Seven top upregulated emRNAs and related to ccRCC or/and multiple malignant tumors, including CUL9, ATM, ARID1A, KMT2D, PBRM1, PREX2, and SETD2, were selected as candidate biomarkers for further testing." (PMID 36002886, 2022). "SETD2 knockdown would lead to the abundance of the IIIb relative to the IIIc transcripts in NCI H522 and NCI H1299 cells and then attenuate cancer cells migration, invasiveness, and proliferation in the presence of FGF-2." (PMID 34715919, 2021). "Therefore, it is necessary to clarify how SETD2 is involved in oncogenesis, progression and prognosis of cancers, which may help select the most appropriate and cost-effective therapeutic drugs, and monitor recurrence and drug resistance, and assess prognosis for each patient." (PMID 32231741, 2020). "SETD2 participates in transcriptional regulation, DNA MMR, human DNA HR and some other processes, leading to progression of malignant tumor." (PMID 32231741, 2020).